BCL2 (BCL2 apoptosis regulator)
Diseases named in the same sentence as BCL2 in open-access papers (continued):
Sharing a sentence is not in itself a finding about the gene and the disease.
cancer (continued). "Given most cancers have deregulated MYC expression, and as a consequence, BCL-2 pro-survival proteins are often also deregulated to counter the pro-apoptotic effect of high MYC expression, there is a strong rationale for co-targeting of MYC and BCL-2 proteins in many cancers." (PMID 33799592, 2021). "In addition, up-regulation of Bax, Bcl-2, and Fas-L mRNA levels in MDA-MB-468, PC-12, and MCF-7 was observed in cancer cell lines." (PMID 34249261, 2021). "In recent years, several BCL-2 protein inhibitors have been developed (Oblimersen, ABT-737, ABT-263, obatoclax mesylate, AT-101, and S55746), to specifically target BCL-2 protein for cancer treatments." (PMID 34768743, 2021). "It was shown that PZH’s anti-cancer activities might be related to the suppression of STAT3 signaling pathways, therefore resulting in the upregulation of Bax/Bcl-2 ratios as well as down-regulation of CCND1 and CDK4 expression." (PMID 33658028, 2021). "Later, it was shown that BCL-2 is essential for the maintenance of cancer cells in a murine model of leukemia, in the first example of the functional removal of a BCL-2 family prosurvival protein resulting in cancer regression." (PMID 33637708, 2021). "The activity of caspase-3 and Bcl-2 protein expression as apoptotic parameters were estimated in all sumac treated and non-treated human cancer cells as shown in." (PMID 33891003, 2021). "Indeed, estrogen-resistant cancer cells overexpress HER2, which results in the constitutive activation of BCL2 by inactivating EZH2 through the AKT pathway." (PMID 33478063, 2021). "Other STAT target genes are involved in cancer signaling to regulate cell proliferation (e.g., cyclin D, HSP90), apoptosis (e.g., BCL-2, MCL-1, Bcl-xL), angiogenesis (e.g., VEGF-A, FGF), metastasis (e.g., MMP1-3, Vimentin, ICAM-1) and signaling (e.g., AKT, PI3K, TNF-R2)." (PMID 34439323, 2021). "They showed a potent activity against Bcl-2-expressing human cancer cell lines, with limited inhibitory activity against a non-Bcl-2-expressing cancer cell line." (PMID 34830153, 2021). "EGCG induces apoptosis in cancer cells through different mechanisms, including the suppression of PI3K/Akt signaling, reduction in mitochondrial membrane potential and expression of anti-apoptotic proteins, including Bcl-2, xIAP, and Bcl-xl." (PMID 34025409, 2021). "WIP1 (PPM1D) has a significant anti-apoptotic effect on uLMS, whereas BCL2 or MCL-1 appear to play little or no role in this cancer cell type." (PMID 35008180, 2021). "Higher levels of Bcl-2 afford a therapeutic window whereby BFCs target and induce apoptosis in resistant cancer cells, without significant effect on normal tissue." (PMID 33804830, 2021). "Hence, we expect it is only a matter of time before such combinations are explored in the clinic, with the hope they can provide benefit for the many cancers that depend on the co-operativity between MYC and BCL-2 proteins." (PMID 33799592, 2021). "Meanwhile, overexpression of IL22 protects NSCLC cancer cell lines from chemotherapy-induced apoptosis via activation of STAT3, which triggers the expression of downstream anti-apoptotic proteins including BCL2 and BCL-xL." (PMID 34944848, 2021). "Cytc release from mitochondria is the driving force for apoptosome leading to apoptotic cell death in several malignant tumor, and VDAC1 has been widely reported to be interacted with pro- or antiapoptotic proteins such as Bcl-2 and HK, whereby mediating the release of Cytc." (PMID 33680287, 2021). "At the same time, DZHSI can reduce the content of Bcl-2 in lung cancer cells and increase the expression of Bax and Caspase 3 to promote the apoptosis of non-small cell lung cancer A549 CELL and play an anti-cancer effect." (PMID 34539390, 2021).
cancer (continued). "Small molecules called BH3 mimetics, that bind into the BH3 binding pocket of the prosurvival proteins BCL-2, BCL-xL, or MCL-1 (as BH3 domains of the proapoptotic ones do), favor mitochondrial apoptosis in cancer cells and have already useful clinical applications." (PMID 32722518, 2020). "Whether ZnO-NPs affect other pro-apoptosis Bcl-2 members (e.g., Bak, Bok, as well as BH3 subfamily Bik, Bim, Noxa, and Puma) with their anti-cancer effect should be further investigated in the future." (PMID 32111101, 2020). "As in many cancer types, BCL2 is highly expressed in CML, particularly in the LSC population, and is perhaps activated by PI3K/AKT and JAK/STAT activity downstream of BCR-ABL1, which supports the development of anti-BCL2 agents to deactivate resistant LSCs54." (PMID 33067577, 2020). "Wnt/β-catenin signaling and expression patterns of important genes in cancer cell growth and survival, which were further suggested to play a role in three-dimensional aggregation, such as NFKB2, VEGFA, CTGF, CAV1, BCL2(L1), or SNAI1, were clearly affected by DEX." (PMID 32033410, 2020). "BCL‐2 and BCL‐XL are the primary targets of ABT‐263 in cancer cells." (PMID 32652830, 2020). "While excellent inhibitors were developed over the years to block the anti-apoptotic defense mechanisms in cancer cells (e.g., BCL-2 and Bcl-xL inhibitors), lack of specific predictive biomarkers for their use has limited their utility." (PMID 32620799, 2020). "AspH inhibition could to some extent account for the observed anti-cancer effects of venetoclax, even though this API inhibits its validated target enzyme, Bcl-2, significantly more efficient than AspH (~1000 fold selectivity)." (PMID 33069066, 2020). "The addition of antioxidant NAC to HCT116 cancer cells decreased the release of cytochrome c and Smac/DIABLO proteins, activation of caspase-3 and -7, and PARP cleavage, as well as phosphorylation of Bcl-2 proteins." (PMID 32098428, 2020). "Moreover, combinations of CDK7i with other targeted cancer therapies, including BET inhibitors, BCL2 inhibitors and hormone therapies, have shown efficacy in model systems." (PMID 32385714, 2020). "Several inhibitors, such as Bcl-2, EGFR, and mTOR, are currently used in cancer treatment." (PMID 33228222, 2020). "However, in various cancers, aberrant STAT5 signalling promotes the expression of target genes, such as cyclin D, Bcl-2 and MMP-2, that result in increased cell proliferation, survival and metastasis." (PMID 32872372, 2020). "Here, we demonstrate that MD has a cytotoxic activity on breast (MCF-7), lung (PC9), and prostate (C4-2B) human cancer cells with an IC50 (μg/mL) of 40, 4.7, and 5 μg/mL, respectively, an increasing Bax/Bcl2 ratio, and inducing a mitochondrial membrane depolarization." (PMID 32121436, 2020). "PI3K/AKT/mTOR inhibition via various molecules or compounds have been shown to induce cancer cell apoptosis through reduction of mitochondrial membrane potential, inactivation of XIAP, activation of caspase-3, upregulation of BAX and downregulation of Bcl-2." (PMID 32443471, 2020). "Nuclear export of NR4A1 elicits non-genomic pro-apoptotic function in cancer cells by direct interaction with B-cell lymphoma 2 (Bcl-2) and exposure of Bcl-2 Homolog 3 domain to initiate the intrinsic apoptosis pathway." (PMID 33172112, 2020). "There are several publications demonstrating changes in bcl-2 in the presence of ART, either in PBMC from PLWH or in cancer cell models, but the effects of the antiretrovirals are varied, suggesting a drug-, cell- and/or disease process type-specific effect of antiretrovirals on bcl-2." (PMID 32526847, 2020). "The observed up-regulation of several miRNA (miR-381-3p, miR-93-5p, miR-16-5p and miR-497-5p) in cancer-infiltrated LVs may inhibit Vascular Endothelial Growth Factor (VEGF) expression or VEGF receptors, both directly and indirectly via Bcl-2 inhibition." (PMID 32716937, 2020).
cancer (continued). "The anti-cancer drugs ABT263 and ABT737 can alleviate the senescence of lung fibroblasts by blocking the up-regulation of Bcl-2 family anti-apoptotic proteins, including Bcl-2, Bcl-XL, and Bcl-W." (PMID 33324646, 2020). "In the present study, the bcl2 expression between the FD extract groups and the cancer control group was observed to be not significant." (PMID 32104177, 2020). "These pleiotropic effects mean that targeting BCL-2 and BCL-2-like proteins may have a multitude of effects on cancer cell fate, and these consequences on anti-cancer therapy remain under investigation." (PMID 32131385, 2020). "On the other hand, DHPS expression appeared to correlate positively with sensitivity to other agents, such as NAMPT, BCL2, and MDMX inhibitors, indicating that DHPS level can be used as a predictive biomarker for response to several different anti-cancer agents." (PMID 32989218, 2020). "Thus, the use of Bcl-2 protein-targeting drugs as single agents or in combination with current standard-of-care therapies could represent a concrete opportunity to overcome therapy-resistant/recurrent solid tumors and to increase the disease-free survival of cancer patients." (PMID 32455818, 2020). "Paraptosis is attractive as an anticancer death pathway because it is independent of pro-apoptotic Bcl-2 proteins and effector caspases, which are frequently downregulated in cancer cells." (PMID 32242030, 2020). "Effect of conjugates 6e and 6f on the expression levels of Bcl-2 and Bax in MCF-7 cancer cells." (PMID 32349307, 2020). "We recently reported that IGF-1 induces a transcriptional programme for mitochondrial biogenesis, while also inducing expression of the mitophagy receptor BCL2/adenovirus E1B 19 kDa protein-interacting protein 3 (BNIP3), suggesting that IGF-1 has a key mitochondria-protective role in cancer cells." (PMID 31936236, 2020). "In triple negative breast (TNBC) cancer cell lines, HHT was demonstrated to strongly decrease survival influenced by MCL-1, BCL-2, SURVIVIN, XIAP and could reduce cancer growth of MDA-MB-231 xenografts." (PMID 32151059, 2020). "In addition, we observed an increase in the ratio of Bcl-2/BAX which are important regulators of cell survival and play an important role in development of cancer." (PMID 33251127, 2020). "In cancer cells under starvation, C-Jun N-terminal protein kinase 1 (JNK1) becomes activated and phosphorylates Bcl-2, disrupting the Bcl-2/Beclin-1 complex and promoting autophagy due to the activation of core autophagic components by isolated Beclin-1 as a response for cell protection." (PMID 33194736, 2020). "The best example of the key role of non-coding RNAs in the development of new drugs for cancer treatment is provided by the venetoclax, a powerful, specific and well tolerated drug that compensates for the lack of miR-15a/miR-16-1 targeting of BCL2 in CLL." (PMID 32098192, 2020). "Effect of bis-indoles 7e and 9a on the expression levels of Bcl-2 and Bax in MCF-7 cancer cells." (PMID 32252280, 2020). "Altogether, these results indicate that BDA-366 does neither trigger cytosolic Ca2+ mobilization by itself nor modulate the ER Ca2+ content in Bcl-2-dependent cancer models." (PMID 32943617, 2020). "REM sleep loss also affected several genes such as prostaglandin-endoperoxide synthase (Ptgs2), B-cell lymphoma 2 (Bcl-2), Proto-Oncogene, Tyrosine Kinase receptor (Kit), KRAS Proto-Oncogene (K-Ras), and Fos Proto-Oncogene (Fos), which are marked in cancer pathways." (PMID 33114225, 2020). "Herein, and as opposed to cancer treatment, sunitinib increased renal Bcl-2 levels and reduced those of caspase-3." (PMID 33212804, 2020). "As such, BDA-366 provoked cell death in cancer cells expressing high levels of Bcl-2, such as SCLC and non-SCLC (NSCLC) cells." (PMID 32943617, 2020).
cancer (continued). "The pore in the mitochondrial outer membrane is formed by the oligomers of pro-apoptotic Bax or Bak proteins, so the increased expression of the anti-apoptotic proteins Bcl-2, Bcl-XL, or Mcl-1 interacting with the BH3 domain will protect the cancer cells from apoptosis." (PMID 32977472, 2020). "However, cancer cell apoptosis genes such as CDK5RAP1 and BCL2 or iron-sulfur clusters, which protects cancer cells against oxygen to damage a class of iron-dependent proteins such as NSF1, are significantly higher in the “CD74 low” samples." (PMID 33327409, 2020). "A number of target genes, including Bcl-2, Bcl-xL, Slug, Snail, survivin and cyclin D1, which have STAT3 binding sites in their promoters, regulate chemoresistance and radioresistance in a variety of cancer cells." (PMID 32872659, 2020). "Bcl‐2, β3 tubulin and P‐gp can all increase the MDR of cancer cells against taxanes." (PMID 32945069, 2020). "However, dependencies on other pro-survival BCL-2 family members may exist depending on the type of cancer and treatment used, as recently reported data on breast cancer showed a positive correlation between not only MCL-1 but also BCL-2A1 expression and an inverse association with BCL-2 expression." (PMID 32913197, 2020). "Not surprisingly, an increased expression of pro-survival BCL-2 proteins is found in several cancer types." (PMID 32335811, 2020). "Calcium influx could also be sensitizing cancer cells to TRAIL by activating calcineurin, another calcium-activated protein that modulates Bcl-2 activity." (PMID 31685811, 2019). "In some metastatic and cancer stem cells (bladder, colon, lung, and breast carcinomas), phosphorylated STAT3 (pSTAT3) promotes cancer proliferation by upregulating antiapoptotic proteins (BCL-2, BCL-xl), pluripotency markers (OCT4), and proto-oncogenes (MYC)." (PMID 31600993, 2019). "AKT2, BCL2, EWSR1 retrogene and MYCN for their cancer notoriety)." (PMID 30890123, 2019). "However, some cancer cells with high Bcl-2 levels respond poorly to BH3 mimetics, suggesting that Bcl-2 promotes cell survival via a different mechanism." (PMID 29899382, 2019). "In ovarian cancer, BIRD-2 was not able to kill cancer cells by itself but led to sensitization of tumor cells to chemotherapy through a Bcl-2-dependent pathway." (PMID 31888223, 2019). "Triptolide is shown to induce mitochondrial-mediated apoptosis in various cancer cells, through decreased mitochondrial membrane potential, Bax and cytochrome c accumulation, PARP and caspase-3 activation, decreased ATP levels, and Bcl-2 down-regulation." (PMID 31719837, 2019). "The results showed that Bcl-2 was a powerful prognostic factor that was independent of cancer stage." (PMID 30630524, 2019). "Functionally testing this threshold does, provided that cancer cells can be isolated directly from the patient while not altering the Bcl-2 landscape." (PMID 31681471, 2019). "G0S2 promotes apoptosis by interacting with the anti-apoptotic protein Bcl-2, and downregulation of G0S2 expression could be a prime avenue for growing cells, especially cancer cells, in preventing death or growth arrest." (PMID 31888477, 2019). "To identify drugs that could enhance the apoptotic effect of BCL-2/BCL-XL inhibition, while still preserving MYC-dependence, we analyzed the effect of ABT-737 in combinations with small-molecules that target cancer survival pathways." (PMID 30728358, 2019). "Consequently, it was applied in the down-regulation of endogenous genes (BCL2 and GAPDH) of the human cancer cell, showing that TX-2 knocked down expression of the target genes much more effectively than WT-HHRz in both mRNA and protein level." (PMID 30649474, 2019). "BID is also a pro-apoptotic member of the B-cell lymphoma-2 (Bcl-2) group of proteins, which have a high expression level in RCC and may participate in the progression of cancer." (PMID 31739630, 2019).
cancer (continued). "Overexpression of Bcl-2 is related to the malignant behavior and drug resistance phenomena of cancer, since Bcl-2 prevents apoptosis and supports cell viability without promoting cell proliferation, by inhibiting the activity of Bax." (PMID 31024941, 2019). "Thus, inhibitors of MCL1 appear especially attractive for combination with BCL-2 inhibitors for the treatment of T-ALL and other cancers." (PMID 30008477, 2019). "Importantly, our results showed correlation of Bcl-2 and PRDM10 expression in cancers overexpressing PRDM10." (PMID 31143550, 2019). "The inability to effectively target BCL-2 proteins accounts for resistance to bortezomib, rapamycin, cyclin-dependent kinase inhibitors, ABT 737, and death receptor (Fas/TRAIL)-induced apoptosis in various cancers including MM." (PMID 31405035, 2019). "Attempts to find out any possible association of G4 structures with genes reported to undergo epigenetic modifications in various cancer types, yielded evidence that several of these gene promoters exhibit potential G4 sequence (PG4), for example, hTERT, H19, KRAS BCL-2, RET, PARP-1." (PMID 30736345, 2019). "In cancer and cardiomyocytes, ADRB2 inhibits apoptosis mainly through Bcl-2/Bax/caspase-9 pathway." (PMID 31781263, 2019). "A more recent small-molecule Bcl-2 inhibitor, venclexta (ABT-199), which has been approved for acute myeloid leukemia and chronic lymphocytic leukemia, is being investigated for the treatment of multiple cancers including some solid tumors." (PMID 31652965, 2019). "In addition, the interactions of Bcl-2 with cellular pathways, such as Akt and RAS, is also important since it can be a mechanism for evasion of apoptosis and chemoresistance in cancer cells." (PMID 31450613, 2019). "Although CLL shows significant dependency on Bcl-2, other cancers are not as sensitive to inhibiting it alone." (PMID 31681471, 2019). "Although ABT‐199 was shown to kill Bcl‐2‐dependent cancer cells without affecting intracellular Ca2+ signalling, its effects on PACs have not yet been determined." (PMID 30266036, 2019). "Interestingly, H-scores of β-catenin were also found to follow similar trends with H-scores of p68 and NF-κB target genes-Bcl-2, Bcl-xL, Survivin and XIAP in both normal and carcinoma samples." (PMID 31351496, 2019). "For example, chromosomal translocation-induced Bcl-2 overexpression and other amplification cases have been observed in many cancer types, so it is not surprising that the parameter describing Bcl-2 production stands out as the most sensitive one." (PMID 29912904, 2018). "It is important to consider that the observation of high levels of pro-survival BCL-2 proteins in cancer need not necessarily indicate strong apoptotic resistance." (PMID 29769323, 2018). "Bcl-2 is a biomarker for the synthetic lethal interaction of IDF-11774 with ATP6V0C, which is clinically applicable for the treatment of cancer patients with IDF-11774 or autophagy-inducing anti-cancer drugs." (PMID 30420612, 2018). "Our findings demonstrate that BCL2 antagonists exert potent effects on cancer metabolism independent of cell death-inducing effects, and demonstrate a synthetic lethality when these are applied in combination with glycolysis inhibitors." (PMID 29899841, 2018).